RUNX2 (RUNX family transcription factor 2)
Diseases named in the same sentence as RUNX2 in open-access papers (continued):
Sharing a sentence is not in itself a finding about the gene and the disease.
breast carcinoma (continued). "For example, RUNX2 is aberrantly overexpressed in a variety of tumors such as breast cancer, prostate cancer, pancreatic cancer, gastric cancer and melanoma." (PMID 28671946, 2017). "Primary and secondary mammosphere assays were performed to implicate phospho-Ser294 PRs, epidermal growth factor signaling, and RUNX2 in breast cancer stem cell biology." (PMID 28412963, 2017). "A deeper understanding of RUNX2 as a mediator of PR actions in breast cancer also warrants future study." (PMID 28412963, 2017). "Following the same mechanism, SIRT6 in breast cancer cells is repressed by runt-related transcription factor 2 (RUNX2) transcription factor, and thus results in a higher rate of glycolysis and the inhibition of mitochondrial respiration." (PMID 27659520, 2017). "RUNX2 and its target genes are highly expressed in breast cancer tissues and play pivotal roles in breast cancer bone metastasis." (PMID 28978036, 2017). "Recently, a correlation between autophagy and the expression of Runx2, a Runt-related transcription factor involved in cell survival during metabolic stress and breast cancer progression, was uncovered." (PMID 29145850, 2017). "Selected phospho-PR-driven target genes were validated by qRT-PCR and following RUNX2 shRNA knockdown in breast cancer cell lines." (PMID 28412963, 2017). "Runx2 promotes the metastatic spread of mammary tumors to the bone, which is a recurrent location for TNBC and luminal breast cancer metastasis." (PMID 29145850, 2017). "Conversely, RUNX2 knockdown in MDA-MB-231 cells, a bone metastatic breast cancer cell line with high RUNX2 expression, down-regulated the expression of these BRGs." (PMID 27806311, 2016). "Overexpression of Runx2 drove EMT–like changes in normal mammary epithelial cells, whereas its deletion in basal breast cancer cells inhibited cellular phenotypes associated with tumorigenesis." (PMID 26621833, 2016). "In patient-derived breast cancer clinical specimens, patients with combined Runx2/Snail positivity have shortened disease-free survival when compared to those with either Runx2-only or Snail-only positivity." (PMID 27023622, 2016). "RUNX2 also contributes to the inhibition of osteoblast differentiation in breast cancer bone metastasis, depending on the primary tumor microenvironment and the bone microenvironment induced by metastatic cancer cells." (PMID 27806311, 2016). "Runx2 has been shown to be a regulator of epithelial cell fate in mammary gland development and breast cancer." (PMID 26621833, 2016). "In breast cancer, RUNX2 mediated the interaction of cancer cells with bone microenvironment and promoted osteolytic destruction, partly by up-regulating the invasion-related gene MMP13." (PMID 27007162, 2016). "miR-135b has been shown to impair breast cancer progression and metastatic osteolytic bone disease via targeting Runx2." (PMID 26995755, 2016). "In basal-type breast cancer cell lines RUNX2 promotes an osteomimetic phenotype and metastasis to the bone through transcriptional activation of osteopontin, MMPs, and VEGF." (PMID 26320173, 2015). "Since high HER2 and RUNX2 status are independent poor prognostic factors in breast cancer, both parameters together seems to be a novel and combined indicator for prognosis assessment and further studies on the cooperation of both these factors are justified." (PMID 26404249, 2015). "Overexpression of RUNX2 in MCF7 breast cancer cell line induced epithelial to mesenchymal transition (EMT), with dependence on Wnt and Tgfβ signaling pathways." (PMID 26404249, 2015). "While estrogen is known to induce breast tumor progression in situ, it also displays an anti-metastatic action, acting in an opposite way to RUNX2, promoting breast cancer cells invasion in vitro." (PMID 26404249, 2015). "RUNX2 can promote breast cancer development through Wnt and Tgfβ signaling pathways, especially in estrogen receptor (ER)-negative cases." (PMID 26404249, 2015).
breast carcinoma (continued). "RUNX2 is an integral part of TGFβ-mediated PTHrP and cyclin D1 gene regulation in breast cancer cells, facilitating the vicious cycle of cancer cell survival and osteolytic disease." (PMID 26204939, 2015). "RUNX2 appears to be involved in the pathogenesis of several cancer types and it seems that its role in breast cancer is complex and can be strongly bound to estrogen signaling." (PMID 26404249, 2015). "Exploring the role of RUNX2 in the pathogenesis of breast cancer can lead to revealing new therapeutic targets." (PMID 26404249, 2015). "Intriguingly, RUNX2 expression in the WNT-driven models of squamous metaplastic breast cancer was limited to the tumour cells positioned in the basal layer of the lesions." (PMID 26489514, 2015). "In a clinical setting, RUNX2 was found to be highly expressed in a small percentage of human breast cancers where expression correlates with triple-negative (ER-, PR-, HER2-) disease." (PMID 26489514, 2015). "It is noteworthy that, in one study, RUNX2 elevated expression was observed in only a subset of breast cancers." (PMID 26404249, 2015). "It is therefore interesting that we find RUNX2 to be strongly expressed in WNT-driven mouse models of breast cancer." (PMID 26489514, 2015). "The expression analysis of Runx2 and pAkt (serine 473) proteins in metastatic breast cancer specimens was performed by immunohistochemistry." (PMID 24479521, 2014). "In order to clarify the relationship between RUNX2 and miR-10a/b, RUNX2 was overexpressed in high and low RUNX2 expressing breast cancer cell lines, MDA-MB-231 and MCF7." (PMID 25266482, 2014). "Despite being known to regulate specific mammary genes and being expressed in some breast cancer cell lines, very little is known about the normal function of RUNX2 in mammary gland development." (PMID 24626992, 2014). "Work on well-characterised breast cancer cell lines has shown that RUNX2 can influence the behaviour of these cells and the response of host tissues following orthotopic injection to bone, but this work has been limited to a few cell lines." (PMID 24626992, 2014). "XRCC6 interacts with Msx2 (a known TBX3 interactor) and Runx2 (a TBX3 target) and mutations in XRCC6 are associated with breast cancer risk and estrogen exposure." (PMID 24675841, 2014). "To investigate the role of this gene in breast cancer, we made a transgenic model in which Runx2 is specifically expressed in murine mammary epithelium under the control of the mouse mammary tumour virus (MMTV) promoter." (PMID 24626992, 2014). "We found that, the expression of RUNX2 and miR-10a/b in ER- and triple negative breast cancer was higher than in ER + breast cancer." (PMID 25266482, 2014). "The RUNX2 transcription factor, known to be oncogenic in the T-cell lineage, is upregulated in human breast cancer cell lines and correlates with invasive properties in these cells." (PMID 24626992, 2014). "The Runt-related transcription factor Runx2 is critical for skeletal development but is also aberrantly expressed in breast cancers, and promotes cell growth and invasion." (PMID 24479521, 2014). "We further validated the effect of Runx2 knockdown on cell death in another invasive breast cancer cell line, SUM-159-PT." (PMID 24479521, 2014). "In a breast cancer cell line, RUNX2 silencing reduced the expression of miR-10a/b and also impaired cell motility, while RUNX2 overexpression elicited opposite effects." (PMID 25266482, 2014). "Using qPCR analysis, we determined the expression levels of RUNX2 and miR-10a/b in 4 breast cancer cell lines." (PMID 25266482, 2014). "Through in vitro experiments, our study demonstrates the impact of RUNX2 on breast cancer migration and invasion and its regulation of miR-10a/b expression." (PMID 25266482, 2014). "Altogether, these results indicate that Runx2 activates Akt signaling and increases survival of invasive breast cancer cells in serum- and glucose starvation-induced cell death." (PMID 24479521, 2014).
breast carcinoma (continued). "They report that high expression of RUNX2 is limited to a small number of primary operable breast cancers." (PMID 24626992, 2014). "RUNX2 is upregulated in metastatic breast cancer cell lines and its inhibition in MDA-MB-231 cells reduces invasive capacity in vitro, and decreases osteolytic disease and tumour growth in vivo." (PMID 24626992, 2014). "The recruitment of Runx2 on mTOR promoter coupled with Runx2-dependent expression of mTORC2 component Rictor defined Runx2 function in pAkt-mediated survival of invasive breast cancer cells." (PMID 24479521, 2014). "To assess the role of RUNX2 in breast cancer we assessed expression in a human tissue microarray (TMA)." (PMID 24626992, 2014). "We examined one hundred and eight patients with histologically proven breast cancers to delineate the relationship between the expression of RUNX2 and miR-10a/b, and clinical outcomes." (PMID 25266482, 2014). "Altogether, our findings indicate a novel Runx2 function in cell survival by regulating Akt signaling in invasive breast cancer cell lines." (PMID 24479521, 2014). "Expression levels of RUNX2 and miR-10a/b individually or jointly are potential prognostic factors for predicting breast cancer recurrence." (PMID 25266482, 2014). "In this study, we showed that RUNX2 upregulated miR-10a/b and promoted breast cancer cell migration and invasion." (PMID 25266482, 2014). "High levels of Runx2 have been reported in breast cancers that correlated with clinical stage, histological grade and Her2 status in clinical breast cancer specimens." (PMID 24479521, 2014). "This is consistent with the report that RUNX2 silencing reduced cell motility of metastatic breast cancer cell line, MDA-MB-231." (PMID 25266482, 2014). "Higher expression of these three genes were significantly correlated with the hazard ratio for breast cancer recurrence (RUNX2: 3.02, 95% CI = 1.50 ~ 6.07; miR-10a: 2.31, 95% CI = 1.00 ~ 5.32; miR-10b: 3.96, 95% CI = 1.21 ~ 12.98)." (PMID 25266482, 2014). "In this study, we try to decipher the relationship between RUNX2 and miR-10a/b in clinical breast cancer samples as well as in cell lines." (PMID 25266482, 2014). "We find that RUNX2 is overexpressed in a particular subset of breast cancers that are oestrogen receptor (ER)/progesterone receptor (PR)/HER2-negative, and that high expression of RUNX2 is associated with poorer patient survival." (PMID 24626992, 2014). "Overall, the findings reported in this paper suggest a clinically relevant role for RUNX2 in breast cancer that is worthy of further investigation." (PMID 24626992, 2014). "RUNX2 cooperates with Smads to induce differentiation of osteoblasts and expression of collagenase in breast cancer cells." (PMID 22966907, 2012). "Recent studies on breast cancer cells disclosed that ER-α physically binds RUNX2 and inhibits expression of several RUNX2 target genes, providing a strong antagonistic correlation between the two genes in a different cellular type." (PMID 23186169, 2012). "The Runt-related transcription factor 2, Runx2, is a master-regulator of bone development and an important determinant of bone metastasis in breast cancer cells." (PMID 22032690, 2011). "We have previously demonstrated that Runx2 requires the co-activator core binding factor beta (CBFβ) to regulate gene expression in breast cancer cells." (PMID 22032690, 2011). "To this end we established that Runx2/CBFβ regulates the expression of genes that mediate both the activation of osteoclasts and the inhibition of osteoblasts by metastatic breast cancer cells." (PMID 22032690, 2011). "This analysis identified the osteoclastogenic cytokines IL-11 and granulocyte-macrophage colony-stimulating factor (GM-CSF) as new Runx2/CBFβ targets in breast cancer cells." (PMID 22032690, 2011). "Runx2 contributes to the ability of breast cancer cells to activate osteoclasts by up-regulating the expression of Indian Hedgehog (IHH)." (PMID 22032690, 2011).
breast carcinoma (continued). "This study demonstrates that Runx2 and CBFβ are required for the expression of genes that mediate the ability of metastatic breast cancer cells to directly modulate both osteoclast and osteoblast function." (PMID 22032690, 2011). "MCF7/Rx2dox breast cancer cells were engineered with a lentivirus expressing Runx2 in response to doxycycline (dox)." (PMID 22151997, 2011). "The aim of this study was to identify genes regulated by Runx2/CBFβ that contribute to the ability of metastatic breast cancer cells to modulate the activity of bone cells." (PMID 22032690, 2011). "We propose that in addition to IHH and OPN, Runx2 mediates stimulation of osteoclast activity by up-regulating the expression of the osteoclastogenic cytokines IL-11 and GM-CSF in metastatic breast cancer cells." (PMID 22032690, 2011). "We also identified the osteoclast activators IL-11 and granulocyte-macrophage colony-stimulating factor (GM-CSF) as new target genes of Runx2/CBFβ in metastatic breast cancer cells." (PMID 22032690, 2011). "In breast cancers, Runx2 is aberrantly expressed and inhibition of Runx2 function in metastatic breast cancer cells transplanted to bone prevents the formation of osteolytic lesions." (PMID 22032690, 2011). "The aim of this study was to determine how Runx2 mediates the ability of metastatic breast cancer cells to modulate the activity of bone cells." (PMID 22032690, 2011). "The aim of this study was to identify Runx2/CBFβ-regulated genes that contribute to the ability of metastatic breast cancer cells to modulate the activity of bone cells." (PMID 22032690, 2011). "The Runt-related transcription factor 2, Runx2, is an important determinant of bone metastasis in breast cancer." (PMID 22032690, 2011). "Runx2 is known to mediate activation of osteoclast activity and inhibition of osteoblast differentiation by metastatic breast cancer cells." (PMID 22032690, 2011). "We also show that Runx2/CBFβ regulates expression of the Wnt antagonist sclerostin and thus reveal a mechanism by which Runx2 mediates osteoblast inhibition by breast cancer cells." (PMID 22032690, 2011). "We also show that Runx2-dependent inhibition of osteoblast differentiation by breast cancer cells is mediated through the Wnt antagonist, sclerostin." (PMID 22032690, 2011). "CBFβ stimulates DNA-binding of the Runt domain, and is essential for most of the known functions of Runx2, including activation of Runx2-regulated genes in breast cancer cells." (PMID 22032690, 2011). "Runx2 and CBFβ are required for the expression of genes that mediate the ability of metastatic breast cancer cells to directly modulate both osteoclast (GM-CSF, IL-11) and osteoblast (sclerostin) function." (PMID 22032690, 2011). "Previous reports showed that Runx2 expression in metastatic breast cancer cells, and in prostate cancer cells, also contributes to their ability to inhibit osteoblast differentiation." (PMID 22032690, 2011). "The expression of two genes, Matrixmetalloproteinase-13 (MMP-13) and Matrixmetalloproteinase-9 (MMP-9), that are known to be involved in invasion and have been shown to be regulated by Runx2 in metastatic breast cancer cells, was examined." (PMID 20591170, 2010). "We show that CBFβ is expressed in the metastatic breast cancer cells, MDA-MB-231, and that it associates with Runx2." (PMID 20591170, 2010). "Runx2 is overexpressed in breast cancer cell lines that metastasize to bone where it has an established role in invasion." (PMID 20591170, 2010). "In search for hints to explain the high predilection of prostate and breast cancer to metastasize to bone, investigators have noticed ectopic expression of Runx2 and some of its target genes in biopsies from advanced tumors and their derivative cell lines." (PMID 20863401, 2010). "Since these receptor proteins are targeted by many drugs for prostate and breast cancer, it is important to investigate their effects on Runx2-regulated transcription." (PMID 20863401, 2010).
breast carcinoma (continued). "We also demonstrated that the metastatic genes OPN and Galectin-3 are Runx2-targets in metastatic breast cancer cells." (PMID 20591170, 2010). "Among the osteomimetic properties of prostate and breast cancer cells are expression of the Runx2 target genes MMP9, BSP and VEGFA, as well as induction of mineralization." (PMID 20863401, 2010). "In metastatic breast cancer cells Runx2 is overexpressed and contributes to the invasive capacity of the cells by regulating the expression of several invasion genes." (PMID 20591170, 2010). "Metastatic breast cancer cells frequently and ectopically express the transcription factor RUNX2, which normally attenuates proliferation and promotes maturation of osteoblasts." (PMID 21029421, 2010). "When Runx2 function was inhibited in metastatic breast cancer cells transplanted to bone, tumorigenesis and osteolysis were prevented." (PMID 20591170, 2010). "Our preceding results indicate that RUNX2 is a potential cell growth inhibitor thus raising the question why aggressive human derived breast cancer cells would tolerate induction of RUNX2 gene expression." (PMID 21029421, 2010). "Ablation of Runx2 expression in metastatic breast cancer cells, MDA-MB-231, resulted in down-regulation of metastatic genes and reduced the invasive capacity of the cells." (PMID 20591170, 2010). "Prior studies indicate that RUNX2 is required for osteolytic lesions of either breast cancer or prostate cancer cells upon intra-tibial injection and cell culture models indicate that RUNX2 expression stimulates cell invasion." (PMID 21029421, 2010). "Interestingly, breast cancer cells that metastasize to bone often maintain high levels of both Runx2 and SNAI2, even in the context of elevated ERα expression, highlighting a distinct molecular signature of bone tropism in ER+ disease." (PMID 41596432, 2026). "Previous studies have reported that RUNX2 induces ITGBL1 expression in breast cancer and melanoma." (PMID 40287769, 2025). "Notably, bone-colonizing breast cancer cells further upregulate osteogenic transcription factors like Runx2, promote the release of bone growth factors and cytokines, accelerate tumor growth, and form a vicious cycle." (PMID 41230330, 2025). "Studies have shown that RUNX2 regulates ITGBL1 in breast cancer, colon cancer, and melanoma." (PMID 40287769, 2025). "Another study showed that RUNX2 activates PI3K/Akt signaling through mTORC2 in breast cancer cells." (PMID 40098982, 2025). "We showed that this function constitutes a distinctive feature of the RUNX2 transcriptional program in thyroid and breast cancers, and we suppose it may represent an additional level of phenotypic plasticity through which RUNX2 promotes cancer metastasis." (PMID 41174748, 2025). "Multiple miRNAs have been shown to modulate Runx2 in breast cancer bone metastasis." (PMID 41230330, 2025). "In vivo and ex vivo experiments in breast cancer models demonstrate that Runx2 is the key driver that makes cancer cells able to preserve their acquired mechanical properties from the site of the primary tumor to the metastatic sites of softer microenvironments." (PMID 38791330, 2024). "Interestingly, we found that in human breast cancer samples, Runx2 and Skp2 are significantly increased and miR-137 and miR-340 are decreased, which is in line with the findings from the FS to BD diet comparison." (PMID 38059614, 2024). "Similarly, heightened expression of RUNX2 is indicative of a poor prognosis in breast cancer patients." (PMID 38430423, 2024). "Additionally, in breast cancer, RUNX2 recruits the NuRD(MTA1)/CRL4B complex to catalyze histone deacetylation and ubiquitination, affecting a cohort of key genes including PPARα and SOD2, which play pivotal roles in promoting EMT and metastasis." (PMID 38430423, 2024). "In addition, opposing roles have recently been suggested for RUNX1 and RUNX2 in controlling the EMT of breast cancer stem cells." (PMID 38630262, 2024).